IL1B (interleukin 1 beta)
Diseases named in the same sentence as IL1B in open-access papers (continued):
Sharing a sentence is not in itself a finding about the gene and the disease.
liver fibrosis (continued). "By stimulating proinflammatory cascades by inflammatory gene expressing and profibrogenic cytokine releasing including Il1b, Tnf, Lgals3, S100a6, S100a4, S100a11, and S100a10, Mac1 was characterized as one of the profibrotic contributors during the liver fibrosis progression." (PMID 37724132, 2023). "When NLRP3 or ARRB2 was successfully silenced, as detected using real-time qPCR and Western blot, we analyzed the mRNA and protein levels of genes related to inflammation and liver fibrosis, including IL-1β, IL-18, p-NF-κB, COL III, FN, and α-SMA in LX-2 cells." (PMID 36983568, 2023). "According to a recent meta-analysis, IL-1β levels were found to be significantly associated with hepatic fibrosis but not with steatosis." (PMID 36768637, 2023). "Moreover, our data revealed that TNF-α/IL-1β upregulated COX-2 expression and PGE2 production, while COX-2 silence reversed the reinforced ability of TNF-α/IL-1β-pretreated hADSCs to attenuate liver fibrosis." (PMID 37095581, 2023). "Moreover, MAMPs and bile acids from the intestine in PBC can promote Kupffer cells to exhibit the M1 phenotype, secrete IL-6, TNF, and IL-1β, and aggravate liver injury and liver fibrosis." (PMID 36969233, 2023). "Given that IL‐1β promotes HSC differentiation into myofibroblasts, it is conceivable that inhibition of IL‐1β by MCC950 may explain the therapeutic effect of NLRP3 inhibition on age‐related liver fibrosis." (PMID 36999514, 2023). "In bile duct ligation (BDL) mice, toxic bile acids further activate NLRP3 inflammasome assembly and cause Kupffer cells to develop the M1 phenotype, leading to the production of proinflammatory cytokines, including IL-6, TNF, and IL-1β, which aggravate liver fibrosis and damage." (PMID 36969233, 2023). "Furthermore, serum S100A8 and pyroptosis-related indicators GSDMD, IL-1β, and IL-18 levels were all gradually augmented during the progression of the liver fibrosis model." (PMID 36429008, 2022). "However, uric acid is also one of the damage-associated molecular patterns (DAMP)-activated proinflammatory cytokines, similar to IL-1b, and IL-18 secretion and activated hepatic stellate cells induced liver fibrosis." (PMID 36556230, 2022). "Moreover, consistent with the human data, GSDMD and IL-1β expression were significantly increased in the liver from the liver fibrosis mouse model compared with the control." (PMID 36429008, 2022). "Elevated IL-1β is strongly associated with increased risk of NAFLD and liver fibrosis." (PMID 36142809, 2022). "An increasing number of studies have confirmed the involvement of inflammasomes in the development of chronic inflammation-induced liver fibrosis, indicating the possibility of therapies targeting inflammasome complex activation as well as signaling pathways involved in IL-1β and IL-18." (PMID 35707547, 2022). "In addition, an in vitro mechanistic study showed that the pyroptosis products IL-1β and IL-18 regulate the activation of hepatic stellate cells (HSCs) and facilitate the development of liver fibrosis." (PMID 36429008, 2022). "Liver injury may retain the active surface of HSCs and accelerate the migration of inflammatory cells to the injured liver, secreting a significant number of inflammatory mediators such as TNF-α, IL-6, and IL-1β to enhance the development of liver fibrosis." (PMID 36017390, 2022). "Since macrophage is an important source of IL-1β in liver fibrosis, we hypothesized that macrophage-derived IL-1β activates mTORC2 in γδ T cells." (PMID 35361750, 2022). "The mRNA levels of liver fibrosis markers (Acta2, Col1a1, Col3a1, and Timp1), cholangiocyte proliferation markers (Krt7 and Krt19), inflammation markers (Il6 and Il1b), and the progenitor cell marker (Sox9) were markedly decreased in miR-200c-BDL mice compared to con-BDL mice." (PMID 34880414, 2022). "Furthermore, serum levels of GSDMD, IL-18, and IL-1β were markedly enhanced in mouse models of liver fibrosis." (PMID 36429008, 2022).
liver fibrosis (continued). "In addition to hepatic stellate cells, infiltrated eosinophils have been shown to induce secretion of pro-inflammatory cytokines IL-18 and IL-1β, or even pyroptotic cell death of hepatocytes, leading to liver fibrosis." (PMID 35673561, 2022). "Besides, regression of hepatic fibrosis is accompanied with a reduction of pro-inflammatory cytokines such as IL-17, and IL-1β in the liver." (PMID 35791909, 2022). "Pelargonidin could prevent liver fibrosis via Nrf2-inhibited ROS/NLRP3/IL-1β axis and inhibit inflammasome-related genes and IL-1β secretion in a dose-dependent manner." (PMID 33552591, 2021). "Together with TGF-1β, IL-1β has also been shown to participate in liver fibrosis." (PMID 32331389, 2020). "In this regard, Kuppfer cell activation leads to the production of many inflammatory cytokines, such as transforming growth factor beta 1 (TGF-b1), nuclear factor kappa-light-chain-enhancer of activated B cells (NF-Kb), and interleukin 1 beta (IL-1 β), related to the liver fibrosis process." (PMID 33187340, 2020). "LCZ696 was superior to valsartan in reducing AST, hepatic fibrosis, tissue IL-1β, TNF-α and NF-κB." (PMID 33173431, 2020). "The decrease of these cytokines reduces the liver damage and the progression of hepatic fibrosis, since IL-1β is related to the amplification of the inflammatory process and contributes to the secretion of profibrogenic cytokine TGF-β, which promotes the activation of hepatic stellate cells." (PMID 32526845, 2020). "The direct regulation mainly occurs through inflammasome expression in hepatic stellate cells (HSCs) to promote hepatic fibrosis, and the indirect pathway for liver fibrosis is regulated by inducing IL-1β and IL-18 secretion in hepatic macrophages to promote HSC activation." (PMID 31429707, 2019). "Our data indicate that significant upregulation of IL1A and IL1B from quiescent HSC due to HCV/HIV co-infection might be an early inflammatory response contributing to enhanced HSC activation leading to hepatic fibrosis." (PMID 30679661, 2019). "Inflammasome activation and IL-1β generation have also been correlated with liver fibrosis." (PMID 31547621, 2019). "Considering our in vitro results and the known predominance of HSCs in the pericentral area, we hypothesized that IL-1β signaling modulates liver fibrosis in an HSC-dependent manner." (PMID 30875826, 2019). "We aimed to determine whether the modulation of IL-1β signaling with IL-1Ra impacts on liver fibrosis." (PMID 30875826, 2019). "IL-1β is mainly produced by TLR-activated macrophages and has potent inflammatory effects; the lack of IL-1α or IL-1β inhibits transformation of steatosis to steatohepatitis and liver fibrosis in hypercholesterolemic ApoE-deficient mice." (PMID 28115795, 2017). "In addition, BAR502 reduced liver fibrosis scores by 70% and expression of pro-fibrogenetic genes (αSMA and α1-collagen), as well as the inflammatory score and liver expression of F4/80, IL-1β, IL-6, MCP-1, RANTES and TNFα mRNA." (PMID 28202906, 2017). "Furthermore, in vivo inhibition of NLRP3 inflammasome with caspase-1 inhibitor dramatically decreased mature IL-1β level of liver tissue and ameliorated liver fibrosis in bile duct ligation (BDL) mouse model." (PMID 27924062, 2016). "Moreover, the western blot result of IL-1β further suggested an enhanced inflammation during the development of hepatic fibrosis." (PMID 24404143, 2014). "Disruption of TLR9, MyD88, or IL-1β signaling significantly attenuates liver fibrosis." (PMID 24340043, 2013). "The constant induction of IL-1β and proinflammatory genes by hepatic macrophages in chronic hepatitis C patients would then serve to recruit immune cells to the liver and augment the inflammatory state resulting in liver fibrosis and cirrhosis." (PMID 23633957, 2013).
liver fibrosis (continued). "In the mouse model of liver fibrosis induced by thioacetamide, ginsenoside was shown to inhibit the entry of IL-1β and IL-18 into the extracellular matrix by regulating ERRα-P2X7r signaling pathway, thereby reducing inflammatory responses, improving hepatocyte damage, and suppressing liver fibrosis." (PMID 39995661, 2025). "Similarly, in vitro studies have shown that IL-1β signaling promotes hepatic lipogenesis and fibrogenesis through activating hepatic stellate cells (HSCs), which are regarded as the key cells promoting hepatic fibrosis." (PMID 40794228, 2025). "Therefore, it has been speculated that IL‐1β genetic polymorphisms promote IL‐1β expression and the development of HCC through inflammation and liver fibrosis." (PMID 38798075, 2024). "Additionally, IL1B contributes to the progression from liver inflammation to liver fibrosis." (PMID 39568749, 2024). "CCl4 treatment could up‐regulate the pro‐inflammatory cytokines TNF‐α, IL‐6 and IL‐1β in the liver, and MulA treatment significantly reduced the levels of these cytokines, indicating that MulA might alleviate liver fibrosis via inhibiting inflammatory cytokines secretion." (PMID 37324833, 2023). "We have previously shown that Notch blockade in macrophages could impair the expression of inflammatory factors interleukin-1 beta (IL1β) and tumor necrosis factor alpha (TNFα) by up-regulation of cylindromatosis (Cyld), and then ameliorate hepatic fibrosis in mice." (PMID 37063432, 2023). "P2X7R-mediated NLRP3 activation involved in IL-1β production by hepatic stellate cells may be associated with extracellular matrix deposition, suggesting that blocking the P2X7R-NLRP3 axis may be a potential therapeutic target for liver fibrosis." (PMID 37081882, 2023). "However, except for Il1β, which has well-known functions during liver fibrosis,40, 41Xaf1, Slfn4, Slfn8, and Ifi213 are profibrotic genes with unknown functions." (PMID 37215993, 2023). "In addition, IL-1β and IL-6 promote hepatocyte injury and liver fibrosis." (PMID 37958712, 2023). "In addition, IL-1β can activate macrophages to produce IL-17 and promote liver fibrosis." (PMID 36969233, 2023). "Similarly, our results showed that TFPCP could ameliorate the inflammatory response (TNF-α, Il-6 and IL-1β) in a CCl4-induced liver fibrosis rat model." (PMID 38074148, 2023). "Therefore, high-dose OCA may have resulted in hepatic fibrosis via cholesterol accumulation and increased the production of IL-1β in an FXR-mediated manner." (PMID 35614939, 2022). "Negligible changes in Il1b transcript levels and comparable level of liver fibrosis in NLRC5-deficient livers suggest that NLRC5-dependent NLRP3 inflammasome activation plays little pathogenic role in liver fibrosis induced by chemically induced hepatocyte injury." (PMID 34712238, 2021). "Genistein protected against liver fibrosis caused by S. japonicum and decreased the extent of hepatic granuloma via inhibiting activation of NF-κB signaling pathway and led to downregulation of inflammatory cytokines MCP1, TNFα, IL1β, IL4, IL10 in infected mice." (PMID 32410640, 2020). "However, determining whether IL-1β is a contributor or a consequence to liver fibrosis pathogenesis demands further investigation." (PMID 30875826, 2019). "Network pharmacology identified IL-1β, IL-6, and TNF-α as potential targets for YQHX in treating liver fibrosis.The UPLC detected multiple potential active components." (PMID 41296792, 2025). "In the MASH model, LGG primarily exerted its effects by inhibiting the TGF-β/SMAD signaling pathway and reducing the expression of pro-inflammatory factors (e.g., IL-1β, IL-6, TNF-α), thereby mitigating liver fibrosis and inflammation." (PMID 40778202, 2025). "High IL-1β/IL-6 and NLRP3 levels drive liver fibrosis in experimental models of non-alcoholic fatty liver disease (NAFLD) mice." (PMID 40332584, 2025).
liver fibrosis (continued). "The serum aminotransferase (ALT and AST), alkaline phosphatase (ALP), bilirubin (TBIL and DBIL), bile acid, inflammatory cytokines (IL-6, IL-1β, TNF-α) and liver fibrosis indicator (HA, LN, PC-III and IV-C) concentrations were measured by ELISA kits." (PMID 41293246, 2025). "KCs can also release pro-inflammatory cytokines, including TNF-α and IL-1β, and recruit peripheral mononuclear macrophages to the liver through the CCL2/CCR2 axis, further aggravating liver fibrosis." (PMID 39635524, 2024). "Some studies have further confirmed that KCs depletion can not only inhibit the production of IL-1β and TNF-α but also inhibit the activation of HSC, thereby alleviating liver fibrosis in a bile duct ligation (BDL)-induced liver fibrosis mouse model." (PMID 39635524, 2024). "The patients with liver fibrosis had significantly higher positivity for α-SMA and IL-1β by immunohistochemistry than normal subjects." (PMID 38172440, 2024). "Increased IL-1β secretion upregulates TIMP-1, inhibiting extracellular matrix degradation and fibroblast apoptosis and aggravating liver fibrosis." (PMID 38595921, 2024). "These indicate that IL‐1β is involved in tumor promotion by immune escape and EMT as well as inflammation and liver fibrosis." (PMID 38798075, 2024). "Th17 cells drive liver fibrosis in schistosomiasis by secreting IL-17, which activates TGF-β signaling and collagen deposition, along with TNF-α and IL-1β that boost hepatic stellate cell activation." (PMID 39700261, 2024). "Previous researches have suggested that COL8A1, IL-1β and OLR1 were involved in the process of liver fibrosis." (PMID 39741334, 2024). "As liver fibrosis advances, the mRNA level of FGF21 gradually increases, and Interleukin (IL)-1β, through the NF-κB and JNK pathways, gradually enhances the expression of FGF21, thereby inhibiting liver fibrosis." (PMID 39267721, 2024). "It is well documented that the activation of the NLRP3 inflammasome/IL-1β axis can lead to pyroptosis of HSC, thereby exacerbating liver injury and eventually leading to hepatic fibrosis." (PMID 39372196, 2024). "The vitamin E also plays a critical role in regulating the inflammatory response by inhibiting the expressions of IL‐1β, MCP and IL‐6, thus attenuating liver fibrosis." (PMID 38652023, 2024). "Univariate regression analysis showed that low mean relative gene expression levels of IL-1β (p < 0.001) and NLRP3 (p = 0.017), and high NFS (p = 0.004) were independent factors for hepatic fibrosis in MAFLD patients." (PMID 39179677, 2024). "This action on TAB2, which recognizes K63-linked ubiquitin chains of RIP1 in TNF-α signaling or TRAF6 in IL-1β signaling, consequently inhibits the TAK1-MAPK cascade, a pathway critical in liver fibrosis progression." (PMID 37867509, 2023). "Marked hepatic fibrosis developed in CDAA-fed group, but IL-1β inhibition affected fibrosis only at transcriptomic level." (PMID 36611037, 2023). "IL-6, TNF-α, MCP1, and IL-1β are the inflammatory cytokines responsible for NASH progression, which play an important role in hepatic fibrosis." (PMID 37762300, 2023). "The potential application of mLO(-DAPT/D3) for the modeling of liver fibrosis was then examined after sustained exposure to a fibrosis-inducing cytokine cocktail (FIC, a mixture of TGFβ1, TNFα, IL-6, and IL-1β)." (PMID 36737811, 2023). "The release of IL-1β from HSC leads to the secretion and deposition of ECM, which is crucial in HSC activation and liver fibrosis." (PMID 37513321, 2023). "Based on the results, VSC-CDs in various dosage groups significantly diminish the levels of TNF-α, IL-6, and IL-1β, signifying that VSC-CDs inhibit the inflammatory response and thereby alleviate liver fibrosis." (PMID 38116381, 2023). "Recently, administering LNA-anti-miR-132 in mice has been shown to attenuate CCL4-induced inflammatory mediators IL-1β and COX2 to alleviate liver fibrosis." (PMID 35163786, 2022).
liver fibrosis (continued). "Interleukin-1 beta (IL-1β) contributes to hepatic injury and fibrosis and AT1 blockade has been shown to decrease hepatic fibrosis in patients with NAFLD." (PMID 36142809, 2022). "In this context, the authors indicated that IL-17 levels (as a part of other secreted ILs as IL-6, IL-10, IL-21, IL-1β and INF-γ) increased in CHC and its level correlated directly with the degree of liver fibrosis." (PMID 35056005, 2022). "RT-PCR analyses supported these observations by showing that mRNAs of inflammatory mediators, IL-1β, IL-6, MCP-1, MCP-3 and TIMP-1 increased in CCl4- and BDL-induced liver fibrosis, and decreased in BI 113823-treated mice." (PMID 36514072, 2022). "The decrease in pro-inflammatory cytokines (IL-6, IL-1β, and TNF-α) is accompanied by regression of liver fibrosis in CCl4-intoxicated rats." (PMID 35881285, 2022). "P2X7 receptor pharmacological inhibitor SGM-1019 was shown to block IL-1β secretion in KCs, HSC activation, and collagen deposition in human cells from NASH and in the primate model from CCl4-induced liver fibrosis." (PMID 35707547, 2022). "The levels of pro-inflammatory cytokines (IL-1β, IL-6, and TNF-α) showed a significant (P < 0.05) increase after 5 and 9 weeks of hepatic fibrosis induction in rats compared with normal control rats." (PMID 35881285, 2022). "Recent studies have indicated that pro-inflammatory cytokines like TNF and IL-1β secreted by macrophages could also activate HSCs, and maintain the survival of activated HSCs through nuclear factors κB (NF-κB) signaling pathway, which aggravates liver fibrosis." (PMID 35990625, 2022). "Consistent with our previous study and the in vitro findings of the present study, we found that DIM significantly reduced the expression levels of IL-1β, IL-6, COX-2, iNOS, and TNF-α in CCl4-induced liver fibrosis." (PMID 36232707, 2022). "Subsequently, the increase of proinflammatory mediators (i.e., TNF-α, IL-6, and IL-1β) and fibrogenesis markers (i.e., TGF-β1, α-SMA, and collagen I), as well as hepatic fibrosis in NASH stage two, were observed in the fructose group." (PMID 36359236, 2022). "In this study, liver fibrosis was also noted in the SB20 group, while the mRNA expression of the inflammatory factor genes nfkb, il1b, and tnfa increased." (PMID 36860455, 2022). "Liver fibrosis levels were flagrantly higher (p<0.01), and TNF-α, NOD-like receptor protein 3 (NLRP3), caspase-1, interleukin-18 (IL-18), and interleukin-1β (IL-1β) protein or gene expression were manifestly up-regulated (p<0.01)." (PMID 35195182, 2022). "Activation of proinflammatory cytokines and chemokines, including IL-6, IL-1β, TNFα, and MCP-1, can activate HSCs, promote ECM secretion and deposition, and then exacerbate liver fibrosis." (PMID 35525986, 2022). "Liver inflammation and ECM deposition are relieved in hepatocyte-specific caspase-11-deficient mice with high sucrose and high fat diet, where the production of IL-1β and GSDMD was blocked, further proving the role of inflammasomes in liver fibrosis." (PMID 35707547, 2022). "Algandaby also showed that crocin (25 and 100 mg/kg) attenuates the expression of TGF-β, alpha-smooth muscle actin (α-SMA) and collagen 1-α, NF-κB, COX-2, IL-1β, and TNF-α following thioacetamide-induced liver fibrosis in mice." (PMID 34956439, 2021). "In order to further prove the effect of apigenin on mouse liver fibrosis, mRNA and protein expression of collagen 1, α-SMA, and IL-1β in the mouse liver tissues were measured by real-time PCR, western blotting, and IHC." (PMID 33574836, 2021). "These inflammatory factors contribute to the progression of liver fibrosis, while TNF-α can stimulate collagen synthesis and IL-6 and IL-1β can activate hepatic stellate cells and directly stimulate collagen secretion." (PMID 34899328, 2021).